FGF19 (fibroblast growth factor 19)
Description:
Involved in the suppression of bile acid biosynthesis through down-regulation of CYP7A1 expression, following positive regulation of the JNK and ERK1/2 cascades. Stimulates glucose uptake in adipocytes. Activity requires the presence of KLB and FGFR4.
Tractability: Antibody: its Gene Ontology location is reachable by antibodies, with high confidence; UniProt places it where antibodies can reach, with medium confidence; UniProt predicts a signal peptide or a membrane-spanning region.
Gene: Protein-coding gene on chromosome 11 (69,698,232 to 69,704,660, reverse strand). Ensembl gene ENSG00000162344.
Subcellular location: Secreted
Pathways (Reactome):
Signal Transduction: FGFR4 ligand binding and activation; FRS-mediated FGFR4 signaling; Negative regulation of FGFR4 signaling; PI-3K cascade:FGFR4; PI3K Cascade; PI5P, PP2A and IER3 Regulate PI3K/AKT Signaling; PIP3 activates AKT signaling; Phospholipase C-mediated cascade; FGFR4; RAF/MAP kinase cascade; SHC-mediated cascade:FGFR4; betaKlotho-mediated ligand binding
Disease: Constitutive Signaling by Aberrant PI3K in Cancer
Gene Ontology:
Molecular function: fibroblast growth factor receptor binding; protein binding; growth factor activity
Biological process: fibroblast growth factor receptor signaling pathway; negative regulation of bile acid biosynthetic process; negative regulation of gene expression; positive regulation of cell population proliferation; positive regulation of D-glucose import; positive regulation of ERK1 and ERK2 cascade; positive regulation of JNK cascade; positive regulation of protein phosphorylation; nervous system development; neurogenesis; positive regulation of MAPK cascade; regulation of cell migration; response to ethanol
Cellular component: cytoplasm; extracellular region
Genetic constraint (gnomAD): Loss-of-function variants: 6 observed, 5.26 expected, observed/expected ratio (o/e) 1.14, 90% interval 0.61 to 1.86. That is too few expected variants to judge how well the gene tolerates losing a copy. Missense variants: 234 observed, 243.46 expected, observed/expected ratio (o/e) 0.96, 90% interval 0.86 to 1.07. Synonymous variants: 124 observed, 109.13 expected, observed/expected ratio (o/e) 1.14, 90% interval 0.98 to 1.32.
Homologues: Orthologues: chimpanzee FGF19 (100% identical), macaque FGF19 (98% identical), dog FGF19 (79% identical), pig FGF19 (76% identical), rabbit FGF19 (72% identical), guinea pig FGF19 (62% identical), rat Fgf19 (49% identical), mouse Fgf15 (48% identical), tropical clawed frog fgf19 (42% identical), zebrafish fgf19 (37% identical). Paralogues in human: FGF21 (32% identical), FGF23 (25% identical), FGF3 (25% identical), FGF5 (24% identical), FGF10 (23% identical), FGF22 (23% identical), FGF7 (22% identical), FGF20 (22% identical), FGF9 (21% identical), FGF4 (20% identical), FGF6 (20% identical), FGF1 (20% identical), and 9 more.
Diseases named in the same sentence as FGF19 in open-access papers:
FGF19 is named in the same sentence as 204 diseases in open-access papers, as found by Europe PMC text mining. Sharing a sentence is not in itself a finding about the gene and the disease. The quoted sentences say what the papers report.
hepatocellular carcinoma (87 papers, 2010 to 2026). A malignant tumor that arises from hepatocytes. "A subset of human hepatocellular carcinomas is driven by abnormal signaling through FGF19 and its receptor FGFR4, which is associated with poor prognosis." (PMID 37108717, 2023). "The major safety concern of the clinical application of wild type FGF19 (FGF19WT) emerges given that its extended treatment causes hepatocellular carcinoma." (PMID 37789318, 2023). "FGF19 has been implicated in the pathogenesis of several cancers, including hepatocellular carcinoma in mice and potentially in humans." (PMID 35719915, 2022). "Preclinical data have shown a higher risk of hepatocellular carcinoma (HCC) in transgenic mice with ectopic expression of FGF19 in the skeletal muscle of transgenic mice." (PMID 32318580, 2020). "Upregulated fibroblast growth factor 19 (FGF19) expression in human hepatocellular carcinoma (HCC) specimens is associated with tumor progression and poor prognosis." (PMID 29973237, 2018). "Recently, FGF19/FGFR4 was reported to cause hepatocellular carcinoma (HCC) in mice, providing further insights into the pathogenesis of the disease in humans." (PMID 27029060, 2016). "The ability of FGF19 to induce hepatocyte proliferation observed in the BrdU incorporation studies has been suggested as the cause for the eventual development of hepatocellular carcinomas in FGF19 transgenic mice." (PMID 22457778, 2012). "Finally, a limitation for using FGF19 in human is the potential risk of hepatocellular carcinoma, as shown in transgenic mice overexpressing FGF1950." (PMID 37015932, 2023). "Additionally, FGF19 is linked to the progression of hepatocellular carcinoma, and FGF23 mediates its effect by activating FGFR1c, FGFR3c, FGFR4, and the α-Klotho cofactor." (PMID 37108717, 2023). "FGF19 has been shown to be involved in EMT in cholangiocarcinoma and colorectal cancer, however, molecular mechanisms underlying FGF19-induced EMT process in hepatocellular carcinoma (HCC) remain largely unknown." (PMID 26498355, 2016). "In recent years, FGF19 has gained attention in cancer research due to its role in various cancers, especially hepatocellular carcinoma (HCC)." (PMID 41328353, 2026). "On the other hand, FGF19 displays a mitogenic activity and has been identified as an oncogenic driver in hepatocellular carcinoma (HCC)." (PMID 38228803, 2024). "In hepatocellular carcinoma, the FGF19/FGFR4 axis was reported to be an oncogenic driver pathway, suggesting it as a promising target." (PMID 38273381, 2024). "In another study, hepatoma cell lines treated with FGF19 (a specific FGFR4 agonist) showed reduced cell proliferation and invasion." (PMID 38540215, 2024). "In hepatocellular carcinoma cells, the expression of hepatitis B virus surface antigen induces ER stress, which increases the expression and secretion of fibroblast growth factor 19 (FGF19) to activate JAK2/STAT3 signaling and induce EMT." (PMID 36890838, 2023). "Various studies reveal that (FGF19) Fibroblast growth factor 19 amplifies HCC (Hepatocellular carcinoma) in patients." (PMID 36677808, 2023). "The expression of FGF19 was significantly elevated in hepatocellular carcinoma patients with a poor prognosis." (PMID 35178126, 2022). "FGF signalling has also been implicated in cell non-autonomous tumourigenesis in the liver, as virally-delivered FGF19 or skeletal muscle-derived FGF19 were shown to be required for the induction of hepatocellular carcinomas in mice." (PMID 34019103, 2021). "A subtype of hepatocellular carcinoma (HCC) expresses FGF19, which activates the FGFR4 signaling pathway that induces cell proliferation." (PMID 33794926, 2021). "Gao and co-workers demonstrated that FGF19/FGFR4 signaling in hepatocellular carcinoma (HCC) cells is one of the main resistance mechanisms to sorafenib, a multikinase inhibitor inducing the ROS (reactive oxygen species)-associated apoptosis." (PMID 34830951, 2021).
hepatocellular carcinoma (continued). "According to previous studies, the FGF19/FGFR4 axis played a pivotal role in many different cancers such as hepatocellular carcinoma, breast cancer, ovarian cancer, and prostate cancer, which led to their low 5-year survival rates." (PMID 34576070, 2021). "The initial evidence of FGF19’s role in hepatocyte growth came from observations in FGF19 transgenic mice who developed hepatocellular carcinomas by 12 months of age." (PMID 35116006, 2021). "Interest in studying FGF19 increased due to its ability to act as a potential biomarker with high sensitivity for hepatocellular carcinoma (HCC)." (PMID 34572066, 2021). "This is in accordance with results reported that ER acts as a moving organelle with many important cellular functions and FGF19 was reported to protect hepatocellular carcinoma cells against ER stress." (PMID 32111983, 2020). "In hepatocellular carcinoma cells, the FGF19/FGFR4 axis has been shown to upregulate ERK/AKT–p70S6K–S6 pathway." (PMID 32111983, 2020). "In patients with hepatocellular carcinoma, high amplification of FGF19 promotes progression and epithelial-mesenchymal transition (EMT) by modulating the GSK3β/β-catenin or STAT3 pathway." (PMID 32111983, 2020). "The selective FGFR4 inhibitor BLU9931 that was used in this study can inhibit FGF19/FGFR4-positive hepatocellular carcinoma tumors." (PMID 33066597, 2020). "The FGF19 gene is occasionally amplified in hepatocellular carcinomas and breast cancer as a consequence of the presence of an amplicon on chromosome 11q13.3." (PMID 33066597, 2020). "Abnormal autocrine fibroblast growth factor 19 (FGF19) production has been observed in several types of cancers, including hepatocellular carcinoma (HCC)." (PMID 31718608, 2019). "FGF19 is a promising therapeutic target for the metabolic syndrome and cholestatic diseases, but enthusiasm for its use has been tempered by FGF19-mediated induction of proliferation and hepatocellular carcinoma." (PMID 28178326, 2017). "FGF19-transgenic mice display increased hepatocyte proliferation at 2–4 months of age and develop hepatocellular carcinoma (HCC) at 10–12 months." (PMID 28178326, 2017). "Overexpression of FGFs was reported, for instance, for FGF8 and FGF19 in hepatocellular carcinoma (HCC) and for FGF2 in multiple cancers including melanoma and mesothelioma." (PMID 29152117, 2017). "Fibroblast Growth Factor 19 (FGF19) neutralizing antibodies inhibit hepatocellular carcinoma (HCC) growth but have safety issues." (PMID 28508871, 2017). "FGF19 was also detected in cirrhosis, a preneoplastic condition that often leads to liver carcinoma." (PMID 26498355, 2016). "This review aims to describe the role of the FGF19/FGFR4 pathway in hepatocellular carcinoma and its role as a potential predictive biomarker for novel targeted agents against FGF19/FGFR4 signalling." (PMID 28943626, 2015). "FGF19-transgenic mice which overexpress FGF19 in skeletal muscle develop multiple hepatocellular carcinomas early in their life, usually by 10–12 months, whilst other tissues are not affected." (PMID 28943626, 2015). "Mitogenic activity has been observed in FGF19 transgenic mice, which developed hepatocellular carcinoma within 12 months and showed increased hepatocyte proliferation as early as 2 to 4 months of age." (PMID 22457778, 2012). "In mice, ectopic expression of FGF19 controls hepatocyte proliferation, hepatocellular dysplasia, and neoplasia, while upregulated FGF19 expression is related to tumor progression and poor prognosis in patients with hepatocellular carcinoma (HCC)." (PMID 41394119, 2025). "However, there are significant safety concerns due to the fact that long-term treatment with wild type FGF19 (FGF19WT) increases hepatocellular carcinoma." (PMID 37789318, 2023). "FGF19 induces proliferation and invasion of hepatocellular carcinoma cell lines." (PMID 35178126, 2022).
hepatocellular carcinoma (continued). "Pharmacological FXR activation and/or therapeutic exploitation of the enterokine FGF19 is known to attenuate not only intestinal inflammation, but also hepatocellular carcinoma, by decreasing circulating BA levels and modulating the BA pool size and composition to a more hydrophilic one." (PMID 35804854, 2022). "A certain subtype of hepatocellular carcinoma (HCC) expresses FGF19." (PMID 33794926, 2021). "FGF19 was first characterized in hepatocellular carcinoma (HCC) as an oncogenic driver." (PMID 33691750, 2021). "However, the molecular mechanisms underlying FGF19/FGFR4 signaling in the antitumor effects to MKIs in hepatocellular carcinoma (HCC) remain unclear." (PMID 33674622, 2021). "Moreover, FGFR4 is not only implicated in RMS tumorigenesis, but drives tumor progression in FGF19 expressing hepatocellular carcinomas, head and neck squamous cell carcinomas, and basal-like breast cancer." (PMID 33182650, 2020). "FGF19 also protects hepatocellular carcinoma cells against endoplasmic reticulum (ER) stress." (PMID 32111983, 2020). "Moreover, CSCs can undergo epithelial-mesenchymal transition (EMT), and FGF19/FGFR4 signaling has been implicated in this process in colorectal cancer and hepatocellular carcinoma." (PMID 33066597, 2020). "It has been attempted by several groups to uncouple the BA regulatory capacity and tumorigenic activity of FGF19 by engineering a M70 mutant (a FGF19 variant) that retains BA regulatory activity without causing hepatocellular carcinoma (HCC)." (PMID 31920680, 2019). "Moreover, although FGF19 has minimal mitogenic activity in fibroblasts in vitro, the skeletal muscles of FGF19 transgenic mice develop hepatocellular carcinoma in a manner dependent on FGFR4 expression." (PMID 31408968, 2019). "Consequently, the pharmaceutical industry is targeting the FGF19 signaling pathway to treat hepatocellular carcinoma (see ClinicalTrials.Gov identifiers NCT00825955 and NCT01215739)." (PMID 29876009, 2018). "In addition, FGF19 overexpression correlated with poor survival outcomes in patients with hepatocellular carcinoma." (PMID 28445152, 2017). "Our results on FGF19-dependent activation of growth-related pathways in the liver are in agreement with previous reports, showing that Fgf15-/- mice develop less hepatocellular carcinoma as compared to Fgf15+/+ littermates, and display impaired liver regeneration." (PMID 28178326, 2017). "Human fibroblast growth factor 19 (FGF19), its receptor (FGFR4) and EpCAM play an important role in cell proliferation, differentiation, motility, and overexpression have been linked to hepatocellular carcinoma (HCC)." (PMID 27447573, 2016). "FGF19 could cooperate with MYC to promote hepatocellular carcinoma development." (PMID 40478912, 2025). "In liver cancer, particularly hepatocellular carcinoma (HCC), FGF19 is found to be notably overexpressed in approximately 5–10% of HCC cases, which implies that FGF signaling plays a crucial role in tumor progression." (PMID 39796710, 2024). "On top of its physiological metabolic role, FGF19 has been identified as a potentially targetable oncogenic driver, notably in hepatocellular carcinoma (HCC)." (PMID 38228803, 2024). "And FGF19 overexpression, which exists in 15% of hepatocellular carcinoma (HCC) patients with amplification of the 11q13 locus, has been proved to be highly associated with carcinogenesis." (PMID 37493315, 2023). "The use of FGF-19 and -15 agonists is discouraged because of their correlation with hepatocyte proliferation, potentially leading to hepatocellular carcinoma (HCC) development in mice." (PMID 35888771, 2022). "The FGFR4 ligand FGF19 is often overexpressed in hepatocellular carcinoma (HCC) due to focal amplification of chromosome 11q13.3." (PMID 34344433, 2021).
hepatocellular carcinoma (continued). "The pro-tumorigenic activity of fibroblast growth factor (FGF) 19 (FGF15 in its rodent orthologue) in hepatocellular carcinoma (HCC), as well as the unsolved problem that ischemia-reperfusion (IR) injury supposes in liver surgeries, are well known." (PMID 34200439, 2021). "Multiple FGFs have been found elevated in different kinds of tumours, such as FGF2 in leukaemia, lung and breast cancer, FGF8 in breast and prostate cancer, FGF10 in lung cancer, FGF19 in hepatocellular carcinoma (HCC) and TNBC." (PMID 33655556, 2021). "FGF19 specifically binds FGFR4 and high FGF19 expression or hyperactivation of FGF19/FGFR4 signalling in hepatocellular carcinoma (HCC) cells is responsible for the resistance to sorafenib, the only TK inhibitor approved for the treatment of this diseases." (PMID 30423915, 2018). "We hypothesized that the constitutive activation of FGFR4 in MDA-MB-468 and HCC1937 could be mediated by an autocrine secretion of FGF19 as has been shown in other cancers, such as hepatocellular carcinomas, lung squamous cell carcinomas, and colon adenocarcinomas." (PMID 27192118, 2016). "This is the first study to elucidate FGF19/FGFR4 signaling in favor of HCC cells developing as indicated by increased EpCAM within the carcinogenesis sequence from fatty liver to hepatocellular carcinoma." (PMID 27447573, 2016). "Moreover, we found that the FGF19 recombinant protein could increase the proliferation (P < 0.01, n = 12) and invasion (P < 0.01, n = 6) capabilities of human hepatocellular carcinoma cell lines and inhibited their apoptosis (P < 0.01, n = 12)." (PMID 22309595, 2012). "In a chronic setting, hepatocellular carcinoma (HCC) formation was observed in 8–10 month old FGF19 transgenic mice." (PMID 22457778, 2012). "Furthermore, our unpublished results show that FGF19 transgenic mice do not develop hepatocellular carcinoma in Fgfr4 deficient background (French DM, in preparation)." (PMID 21437243, 2011). "FGF19 amplification is related to HBV or HCV infection and cirrhosis in HBV‐related hepatocellular carcinoma." (PMID 38545846, 2024). "In hepatocellular carcinoma(HCC) and melanoma, serum FGF19 levels were significantly elevated in tumour patients." (PMID 37782406, 2024). "For instance, drugs based on FGF19 have shown promising results in the selective treatment of patients with PBC, PSC, NASH, or hepatocellular carcinoma (HCC)." (PMID 39682745, 2024). "Aberrant FGF19/FGFR4 signaling pathways (i.e., amplification, mutation, rearrangements, or overexpression) have been detected in a variety of cancers, such as hepatocellular carcinoma (HCC), breast cancer, prostate cancer, and pancreatic cancer." (PMID 36697897, 2022). "The fibroblast growth factor 19 (FGF19)/fibroblast growth factor receptor 4 (FGFR4) signaling pathways play critical roles in a variety of cancers, such as hepatocellular carcinoma (HCC)." (PMID 36697897, 2022). "More importantly, FGF19 signaling through the FGFR4/β-klotho receptor complex has been shown to be a key driver of growth and survival in hepatocellular carcinoma, which makes selective FGFR4 inhibition an attractive therapeutic opportunity." (PMID 33935756, 2021). "The FGF19/FGFR4 axis has also been reported to induce mTORC1 and ERK pathways to converge on S6 in hepatoma cells and in head and neck squamous cell carcinoma (HNSCC)." (PMID 32111983, 2020). "We investigated human FGF19 and FGFR4 expression in 40 hepatocellular carcinoma specimens using quantitative real-time reverse transcription polymerase chain reaction (RT-PCR) analysis and immunohistochemistry." (PMID 22309595, 2012). "Radio-iodinated FGF19 exhibited an affinity with a Kd value of 303 pM to the FGFR1-KLB complex expressed on the T-Rex 293 cells, and 778 pM to a hepatocellular carcinoma cells expressing FGFR4 and KLB." (PMID 22442730, 2012). "FGF19, a fibroblast growth factor, together with CCND1, was recently reported to a major driver oncogene in hepatocellular carcinoma." (PMID 22761904, 2012).